GIP (gastric inhibitory polypeptide)
Diseases named in the same sentence as GIP in open-access papers (continued):
Sharing a sentence is not in itself a finding about the gene and the disease.
Obesity (continued). "In contrast, GIP effects on the VAT of individuals with obesity and prediabetes seem to mirror the effects of GLP-1 by decreasing lactate and alanine production while increasing pyruvate and pyroglutamate consumption." (PMID 37233628, 2023). "The beneficial effect of TZT in T2DM and obesity is related to the direct activation of GIP and GLP-1 receptors with subsequent improvement of insulin sensitivity and reduction of bodyweight." (PMID 37208555, 2023). "Since TZT activates both GIP and GLP-1, it induces a remarkable reduction in body weight, unlike GIPR agonist, which is implicated in the development of obesity when used alone." (PMID 37208555, 2023). "GLP-1/GIP co-agonists are one of the most promising drugs to treat obesity and diabetes and have been shown to reduce fasting cholesterol and triglycerides in T2D patients." (PMID 37592302, 2023). "Considering the favourable metabolic effects of both GLP-1 and GIP, combined therapies with both these incretins have been investigated to improve the efficacy of obesity treatments." (PMID 37378828, 2023). "GIP has received less attention compared to GLP-1 as a therapeutic target in obesity due to early findings that GIP physiologically stimulates glucagon secretion and lipogenesis." (PMID 37249754, 2023). "GIP promotes fatty acid synthesis and glucose uptake in adipose tissue with the development of obesity." (PMID 37208555, 2023). "GIP has long been considered a hormone that promotes obesity; GIP is excessively secreted after nutrient consumption, and it promotes fat deposition in adipose tissue." (PMID 36909312, 2023). "Since then, several other molecules that, along with GLP-1, also target GIP or glucagon receptors have been developed and are currently being tested in clinical trials for the treatment of obesity and other obesity-related disorders, such as T2D." (PMID 37233628, 2023). "In this review, we present the evidence supporting the use of a dual GIP/GLP-1 receptor agonist in the treatment of obesity, highlighting the physiological mechanisms and discussing the preclinical and clinical trials of this drug." (PMID 36909312, 2023). "This has led to controversy about the potential role of GIP in the development of drugs for obesity and related metabolic disorders." (PMID 37049856, 2023). "In mouse models of diet-induced obesity, GLP-1-RA-induced weight loss has been demonstrated to be improved by the co-administration of a long-acting GIP analog." (PMID 36909312, 2023). "Since TZT activates both GIP and GLP-1, it induces remarkable body weight reduction, unlike GIPR agonists, which are implicated in the development of obesity when used alone." (PMID 37208555, 2023). "Another example of an endogenous peptide derived from proglucagon and exhibiting an anti-obesity effect is glucose-dependent insulinotropic polypeptide (GIP)." (PMID 38010450, 2023). "The beneficial effect of TZT in T2DM and obesity is related to direct activation of GIP and GLP-1 receptors with subsequent improvement of insulin sensitivity and reduction of body weight." (PMID 37208555, 2023). "In particular, a defective GIP/GIPR signalling has been observed in the subcutaneous WAT of individuals with obesity and insulin resistance." (PMID 37378828, 2023). "As an important incretin, the peripheral roles of GIP in metabolism, diabetes, obesity, appetite control, and other physiological functions have been well documented in previous research." (PMID 35712239, 2022). "Several studies have demonstrated that GIP-overexpressing mice show increased bone mass and reduced obesity." (PMID 35204073, 2022). "Mistimed eating can also result in the dysregulation of hormones involved in energy metabolism (such as leptin, cortisol, adiponectin, pro-opiomelanocortin, gastric inhibitory polypeptide and others), which can in turn promote obesity." (PMID 36135220, 2022).
Obesity (continued). "Both GLP-1 and GIP increase insulin secretion by pancreatic β-cells, but GIP has also been reported to be an ‘obesity hormone’." (PMID 35440936, 2022). "GLP-1 receptor agonists have been successfully used clinically for T2DM treatment, whereas GIP levels are increased in individuals with obesity and T2DM." (PMID 35571083, 2022). "As East Asian people are well known to show less insulin secretion than white people, hyperinsulinemia and GIP signaling would contribute to obesity differently between them." (PMID 35452190, 2022). "In preclinical models, it had been shown before that dual GLP-1/GCG as well as dual GLP-1/GIP agonists improve metabolic parameters and are capable of fighting obesity." (PMID 36552107, 2022). "While glucose-dependent insulinotropic polypeptide/gastric inhibitory polypeptide (GIP) is known to be involved in high-fat diet (HFD)-induced obesity, the effect of GIP on BCM is still controversial." (PMID 35909510, 2022). "The GIPR is expressed in human adipose tissues, and high levels of circulating GIP are associated with high body mass index (BMI), further supported by a GIPR knock-out mouse model, which is resistant to high fat diet-induced obesity." (PMID 35846282, 2022). "Here, we discuss preclinical and clinical findings in obesity and other therapeutic areas of interest for glucagon, the endogenous incretin hormones GIP and GLP‐1 and GLP‐1R agonists, as well as their actions when combined as dual and triple agonists." (PMID 34713962, 2022). "Hypersecretion of GIP along with its impaired insulinotropic action is common in people with obesity and diabetes mellitus." (PMID 36010335, 2022). "As a result, understanding the mechanism of GIP secretion by nutrients will pave the way for a treatment strategy for obesity and diabetes." (PMID 35452190, 2022). "In the present study, 111In-exendin-4 SPECT/CT was utilized to reveal longitudinal BCM changes in mice with gain- and loss-of-function; obesity under HFD and GIP deficiency." (PMID 35909510, 2022). "GIP, which is secreted by enteroendocrine K-cells, has been reported to be implied in the development of obesity and the pathogenesis of cardiovascular disease." (PMID 35208189, 2022). "The incretin hormones glucagon-like peptide-1 (GLP-1) and glucose-dependent insulinotropic polypeptide (GIP) regulate glucose homeostasis and are recognized as important therapeutic targets for diabetes and obesity." (PMID 35440936, 2022). "Proposed mechanisms that explain the anti-obesity effect of supraphysiological dosing of exogenous long-lasting GIP agonists involved direct GIP action in the brain." (PMID 36010335, 2022). "Other studies reported either lipolytic or lipogenic action of GIP, depending on the obesity status or glucose tolerance." (PMID 36010335, 2022). "Although GIP secretion is increased in obesity, the effect of GIP on in-vivo BCM remains controversial." (PMID 35909510, 2022). "Chronically GIP-overexpressing transgenic mice showed similar effects, suggesting the protection of the pathway against obesity." (PMID 36145148, 2022). "Research has been especially directed towards elucidating the effect of GIP on adipose tissue and its role in the pathogenesis of obesity." (PMID 35710141, 2022). "The observation that global loss of Gipr protects from diet-induced obesity and that GIP can promote adipocyte lipid storage has inspired the development of GIPR antagonists for the treatment of obesity." (PMID 35299971, 2022). "Certainly, the apparent advantage of tirzepatide, a dual incretin agonist, over GLP-1RA will spark renewed interest in the therapeutic potential of GIP in type 2 diabetes, obesity and related co-morbidities." (PMID 36050763, 2022). "Peptide analogues based on a naturally occurring C‐ and N‐terminally truncated GIP variant, GIP(3‐30)NH2, were found to antagonize the GIP receptor and reduced obesity and improved metabolic control in mice." (PMID 35710141, 2022).
Obesity (continued). "As a result of insulin insensitivity, GIP levels rise that increases nutrient absorption and becomes a contributing factor in the onset of obesity." (PMID 35224107, 2022). "Basal concentrations and responses to an oral glucose tolerance test of glucagon, GLP-1, GIP, CCK, and gastrin at baseline and after matched ~6% weight loss by a CD or a CRHP diet in individuals with T2D and overweight or obesity." (PMID 36061897, 2022). "A cooperative exchange of ghrelin and mediators associated with it, such as insulin, leptin, GIP, GLP-1, glucagon, and PAI-1, was revealed, which realizes their effects on obesity." (PMID 33959145, 2021). "While GLP-1/GIP dual-agonists have advanced to phase 3 clinical trials for treating obesity and diabetes, the contribution of GIPR agonism to these applications is questionable." (PMID 33556643, 2021). "Other SCFAs such as butyrate and propionate protected against diet-induced obesity and regulated gut hormones such as glucagon-like peptide-1, glucose-dependent insulinotropic polypeptide (GIP), peptide YY, and ghrelin." (PMID 35126309, 2021). "Mice with GIP receptor (GIPR) depletion are protected from diet-induced obesity, and patients with type 2 diabetes show an impaired insulinotropic response to GIP infusion." (PMID 33556643, 2021). "Hormone-based therapies including GLP-1 and GIP agonists and dipeptidyl peptidase-4 (DPP-4) inhibitors have been linked to reduced obesity." (PMID 34094026, 2021). "This hybridised GLP-1/GIP/glucagon activator was initially developed for management of obesity-diabetes and showed promising preclinical results in rodent models of diabetes-obesity." (PMID 34093449, 2021). "Most macronutrients stimulate both GLP-1 and GIP secretion, and GIP promotes adiposity, an undesirable action during obesity." (PMID 34205659, 2021). "Conversely, in a state of obesity, GIP levels are elevated during both fasting and after an oral glucose challenge, whereas GLP-1 levels are unchanged during fasting and reduced in response to an oral glucose challenge." (PMID 33671882, 2021). "In the epiWAT from mice with obesity, GIP plays an important role in restraining the production of S100A8/A9 in ATMs, and the deficiency in GIPR in myeloid cells augments myelopoiesis and accumulation of S100A8/A9+ neutrophils and ATMs in the epiWAT." (PMID 33717200, 2021). "A monoclonal GIP neutralising antibody prevented weight gain independently of food intake in a mouse model of diet-induced obesity (DIO), reduced fasting insulin concentrations and improved intraperitoneal glucose tolerance." (PMID 33788878, 2021). "Overall, the “incretin effect” has been reported to be decreased in obesity, likely as a result of a reduced responsiveness to GIP or reduced contribution of GLP-1 to the insulin secretory response." (PMID 33671882, 2021). "Further research is needed to verify the therapeutic potential of GIP antagonism in obesity treatment." (PMID 33503878, 2021). "On the contrary, fasting and post-oral glucose tolerance test (OGTT) and GIP concentrations are higher in individuals with obesity than in lean individuals." (PMID 33503878, 2021). "Altogether, these results outline a pivotal role for GIP in balancing fat depot type 2 immune networks during the development of obesity, at least partially through its restraining of the immune cell-derived S100A8/A9." (PMID 33717200, 2021). "Several studies have highlighted the direct relationship between overnutrition, increased levels of GIP, and the development of obesity and its selected metabolic consequences including diabetes." (PMID 32069846, 2020). "Firstly, under conditions of insulin resistance, such as obesity and type 2 diabetes, GIP promotes lipid deposition in subcutaneous adipocytes." (PMID 32436022, 2020). "Analysis of microRNA relative expression revealed the miRNA profile related to high GIP plasma level in obesity." (PMID 32069846, 2020).
Obesity (continued). "However, it remains unclear whether pharmacological concentrations of GIP can induce similar pro-inflammatory changes, or conversely suppress the inflammation because both physiological GIP inhibition and pharmacological GIP administration can similarly induce anti-obesity effects." (PMID 32098413, 2020). "Fat strongly induces GIP secretion, and GIP hypersecretion is involved in high-fat diet-induced obesity and insulin resistance." (PMID 31977316, 2020). "One study showed that GIP infusion increases subcutaneous adipose tissue lipid uptake, an anabolic effect that would exacerbate obesity and insulin resistance in these patients." (PMID 33339298, 2020). "Animal and human studies report a physiological role for GIP in the nutrient uptake into adipose tissues and, therefore, in the pathogenesis of obesity." (PMID 31412576, 2019). "Accordingly, GIP is considered to act as a pro-adipogenic hormone that exacerbates obesity by forming a vicious circle of obesity and hypersecretion of GIP." (PMID 31509948, 2019). "Ambiguity regarding the role of glucose-dependent insulinotropic polypeptide (GIP) in obesity arises from conflicting reports asserting that both GIP receptor (GIPR) agonism and antagonism are effective strategies for inhibiting weight gain." (PMID 31447324, 2019). "The fundamental support for the role of GIP in obesity comes from studies on GIP receptor knockout mice, which, unlike control animals, are protected from obesity and insulin resistance in response to high fat or high-GI diets." (PMID 31412576, 2019). "Understanding the role of this neuronal population responsive to GIP will help the development of new drugs targeting diabetes and obesity." (PMID 31447324, 2019). "In the present study, we investigated GIP secretion in two mouse models of obesity: High-fat diet-induced obese (DIO) mice and leptin-deficient Lepob/ob mice." (PMID 31509948, 2019). "Acute fat ingestion stimulates GIP secretion, while chronic high-fat diet loading enhances GIP secretion and induces obesity in mice." (PMID 31477157, 2019). "Though GIP signaling is attenuated in the subcutaneous adipose tissue under conditions of insulin resistance, it is possible that GIP contributes to obesity by acting on visceral adipose tissue." (PMID 31477157, 2019). "There are mainly 4 targets for obesity vaccines now, including adipose tissue antigens, somatostatin, glucose-dependent insulinotropic polypeptide (GIP), and ghrelin." (PMID 30345314, 2018). "Reversely, inhibition of the GIP signal in GIP receptor knockout (KO) mice prevents insulin resistance as well as obesity." (PMID 28840471, 2018). "GIP has a physiological role for nutrient uptake into adipocytes and is a key molecule linking over-nutrition to obesity." (PMID 28840471, 2018). "Glucose-dependent insulinotropic polypeptide (GIP) is closely related to diabetes and obesity, both of which are confirmed to increase the risk of coronary artery disease (CAD)." (PMID 29765988, 2018). "Similar to the conundrum regarding the clinical use of GIP receptor agonists or antagonists, both genetic knockout and overexpression of GIP has been shown to protect against obesity and development of diabetes." (PMID 28004148, 2017). "A genetic deficit in GIP-secreting K cells enhances energy expenditure and prevents high-fat diet-induced obesity in mice." (PMID 28970776, 2017). "On the other hand, many studies indicate that not only inhibition of GIPR, but also control of GIP secretion is effective for preventing obesity." (PMID 28970776, 2017). "UBE2Z is physically located near GIP gene along chromosome 17, while it is known that GIP plays a protective role in atherosclerosis and obesity." (PMID 28840129, 2017). "Reduction of postprandial GIP secretion can increase postprandial energy catabolism and prevent obesity." (PMID 28970776, 2017).
Obesity (continued). "Accumulated evidence suggests that GIP, through its specific receptor, plays an important role in the onset of obesity by promoting energy storage in adipose tissues." (PMID 27112963, 2017). "Studies have shown that the secretion of GIP increases significantly after the excessive ingestion of nutrients, indicating that GIP plays an important role in the development of obesity and insulin resistance induced by a high-calorie diet." (PMID 27686734, 2016). "GIP has been proposed to have a physiological role in nutrient uptake into adipose tissues, thereby linking overnutrition to obesity." (PMID 26075286, 2015). "The blockade of GIP action appears promising as a new and potentially important approach to treat obesity-related diabetes." (PMID 25141237, 2014). "Basal and stimulated GIP levels are elevated in obesity and type 2 diabetes; type 2 diabetics are suspected to be resistant to the insulinotropic effects of GIP." (PMID 24250335, 2013). "Transgenic mice overexpressing GIP exhibited reduced diet-induced obesity, although excessively elevated levels led to GIP resistance." (PMID 23689510, 2013). "GLP-1 has been reported to be attenuated by obesity while the effect of obesity on GIP is more equivocal." (PMID 23762590, 2012). "Hormones such as leptin, amylin, GIP, and insulin, to which a suggested state of resistance is observed in obesity and T2D tend to decrease, favor a restored homeostasis." (PMID 22619730, 2012). "In contrast, although GIP Tg mice demonstrated enhanced β-cell function, resulting in improved glucose tolerance and insulin sensitivity, they exhibited reduced diet-induced obesity." (PMID 22802954, 2012). "The GIPR ligand, GIP, was shown to promote fatty acid synthesis in adipocytes and to favor obesity in vivo." (PMID 21767385, 2011). "According to a previous study using mice with an inactivated GIP receptor, the duodenal hormone GIP directly links over-nutrition to obesity." (PMID 20470376, 2010). "in mice has shown an interactive role of estrogen and GIP signalling in obesity but the molecular mechanism involved in this interaction still needs elucidation." (PMID 20673334, 2010). "In developing GIP-based therapies for type 2 diabetes a major caveat has been the possibility of GIP promoting obesity." (PMID 20231880, 2010). "Recently published studies of obesity vaccines have shown promise with ghrelin and gastric inhibitory polypeptide (GIP) as candidate targets for weight control." (PMID 20122177, 2010). "Taken together, these observations show the importance of GIP signaling for fat storage rendering GIPR an interesting candidate for obesity." (PMID 19254363, 2009). "Variables that can lead to a dysfunction or act as antagonists of GIP have been shown to reduce obesity and insulin resistance." (PMID 19254363, 2009). "Gastric inhibitory polypeptide (GIP) is postulated to be involved in type 2 diabetes mellitus and obesity." (PMID 19254363, 2009). "Gastric inhibitory peptide (GIP, also known as glucose-dependent insulinotropic polypeptide) has recently been postulated to link over-nutrition with obesity." (PMID 18779862, 2008). "Here we describe a potential new treatment for obesity based on immunoneutralization of GIP, a gut hormone that has recently been shown to link over-nutrition to obesity." (PMID 18779862, 2008). "The emergence of glucagon‐like‐peptide‐1 receptor agonists (GLP‐1RAs) and dual glucose‐dependent insulinotropic polypeptide (GIP)/GLP‐1 receptor agonists has fundamentally transformed obesity management, offering highly efficacious pharmacological approaches to weight loss." (PMID 41145379, 2026). "Both GIPR knockout mice and GIP over‐expressing mice are protected from high‐fat diet–induced obesity, and both GIPR agonists and GIPR antagonists induce moderate weight loss in preclinical obesity models." (PMID 41287212, 2026).